PAWR (pro-apoptotic WT1 regulator)
Description:
Pro-apoptotic protein capable of selectively inducing apoptosis in cancer cells, sensitizing the cells to diverse apoptotic stimuli and causing regression of tumors in animal models. Induces apoptosis in certain cancer cells by activation of the Fas prodeath pathway and coparallel inhibition of NF-kappa-B transcriptional activity. Inhibits the transcriptional activation and augments the transcriptional repression mediated by WT1. Down-regulates the anti-apoptotic protein BCL2 via its interaction with WT1. Also seems to be a transcriptional repressor by itself. May be directly involved in regulating the amyloid precursor protein (APP) cleavage activity of BACE1.
Synonyms: Par-4; PAR4
Tractability: Antibody: its Gene Ontology location is reachable by antibodies, with high confidence. PROTAC: ubiquitination databases record sites on it; its protein half-life has been measured.
Gene: Protein-coding gene on chromosome 12 (79,574,979 to 79,690,964, reverse strand). Ensembl gene ENSG00000177425.
Subcellular location: Cytoplasm; Nucleus
Subcellular location (Human Protein Atlas): Actin filaments; Cytosol; Plasma membrane; Primary cilium tip
Gene Ontology:
Molecular function: enzyme binding; leucine zipper domain binding; protein binding; actin binding; transcription corepressor activity
Biological process: actin filament bundle assembly; apoptotic process; apoptotic signaling pathway; negative regulation of transcription by RNA polymerase II; positive regulation of apoptotic process; positive regulation of neuron apoptotic process; negative regulation of fibroblast proliferation; negative regulation of gene expression; positive regulation of cellular senescence; positive regulation of gene expression; positive regulation of hydrogen peroxide-mediated programmed cell death
Cellular component: cytoplasm; cytosol; nucleus; actin filament; chromatin
Genetic constraint (gnomAD): Loss-of-function variants: 7 observed, 4.25 expected, observed/expected ratio (o/e) 1.65, 90% interval 0.85 to 1.95. That is too few expected variants to judge how well the gene tolerates losing a copy. Missense variants: 300 observed, 182.11 expected, observed/expected ratio (o/e) 1.65, 90% interval 1.5 to 1.81. Synonymous variants: 151 observed, 95.16 expected, observed/expected ratio (o/e) 1.59, 90% interval 1.39 to 1.81.
Homologues: Orthologues: chimpanzee PAWR (99% identical), macaque PAWR (98% identical), pig PAWR (88% identical), rabbit PAWR (85% identical), dog PAWR (81% identical), mouse Pawr (78% identical), rat Pawr (77% identical), guinea pig PAWR (70% identical), tropical clawed frog pawr (46% identical), zebrafish pawr (46% identical).
Diseases named in the same sentence as PAWR in open-access papers:
PAWR is named in the same sentence as 24 diseases in open-access papers, as found by Europe PMC text mining. Sharing a sentence is not in itself a finding about the gene and the disease. The quoted sentences say what the papers report.
prostate carcinoma (10 papers, 2011 to 2021). A carcinoma that arises from epithelial cells of the prostate gland. "PRKC apoptosis WTI regulator (PAWR), also known as Par-4, is a leucine zipper domain protein implicated in various cancers, including prostate cancer, bladder cancer, breast cancer, endometrial cancer, and leukemia." (PMID 33317551, 2020). "Moreover, dsPAWR-433 actually induced growth inhibition and apoptosis of prostate cancer cells, suggesting that the increased PAWR protein by saRNA is physiologically functional and has great potential for the application in cancer therapy." (PMID 34220332, 2021). "In prostate cancer cells, switching from autophagy to apoptosis has been found after treatment with a semi-synthetic analogue, 3-azido derivative of WFA (3-AWFA) due to the pro-apoptotic protein PAWR-mediated suppression of BCL2." (PMID 31731424, 2019).
bladder cancer (2 papers, 2021 to 2022). "PAWR, has been previously shown to be a key altered gene in human bladder cancer stem cells." (PMID 36352089, 2022). "In the present study, we demonstrated that another PAWR promoter targeted dsRNA, dsPAWR-435, could potently induce activation of PAWR gene expression in bladder cancer cells." (PMID 34220332, 2021).
gastric cancer (2 papers, 2022 to 2024). A primary or metastatic malignant neoplasm involving the stomach. "For example, the circular RNA MTO1 slows the progression of gastric cancer by increasing Prostate Apoptosis Response-4 protein (PAWR) levels by sponging miR-199a-3p." (PMID 39293372, 2024). "As for gastric cancer, previous studies exhibit that circ‐MTO1 suppresses its development and progression by regulating microRNA (miR)‐3200‐5p/phosphatidylethanolamine binding protein 1 (PEBP1) axis and miR‐199a‐3p/pro‐apoptotic WT1 regulator (PAWR) axis." (PMID 35478417, 2022).
oligodendroglioma (2 papers, 2015 to 2021). A well-differentiated (WHO grade II), diffusely infiltrating neuroglial tumor, typically located in the cerebral hemispheres. "TCGA and REMBRANT data analysis revealed that low levels of Par-4 correlated with low survival period (21.85 ± 19.30 days) in GBM but not in astrocytomas (59.13 ± 47.26 days) and oligodendrogliomas (58.04 ± 59.80 days) suggesting low PAWR expression as a predictive risk factor in GBM." (PMID 25685660, 2015).
ovarian carcinoma (2 papers, 2020 to 2021). A malignant neoplasm originating from the surface ovarian epithelium. "There was a significant positive correlation between PAWR gene effect and cisplatin sensitivity of ovarian cancer cell lines (R = 0.5973, P = 0.0187)." (PMID 33317551, 2020).
adenoma (1 paper, 2025). A neoplasm arising from the epithelium. "The transcriptional co-regulatory mechanisms pathway was identified, exhibiting DEGs in the adenocarcinoma cohorts compared to adenoma; these genes include CEBPZ, MED10 and PAWR." (PMID 40362431, 2025). "ARRB1 (p = 2.79 × 10−5), CTBP1 (p = 1.33 × 10−5) and CTBP2 genes (p = 0.0002) exhibited notable upregulation in adenoma, whereas COL1A2 (p = 0.0075), CEBPZ (p = 0.0057), MED10 (p = 0.0196) and PAWR genes (p = 0.00215) showed significant upregulation in adenocarcinoma." (PMID 40362431, 2025).
epilepsy (1 paper, 2024). A brain disorder characterized by episodes of abnormally increased neuronal discharge resulting in transient episodes of sensory or motor neurological dysfunction, or psychic dysfunction. "Five feature genes, namely CD38, FAIM2, IL1B, PAWR, and S100A8, were identified as diagnostic biomarkers for epilepsy subtyping, forming the basis for constructing a disease classification model." (PMID 38384278, 2024). "Combining the results of both algorithms, we identified five feature genes (CD38, FAIM2, IL1B, PAWR, S100A8) as diagnostic biomarkers for epilepsy grouping." (PMID 38384278, 2024).
melanoma (1 paper, 2021). A malignant, usually aggressive tumor composed of atypical, neoplastic melanocytes. "Investigating negative-regulated target genes, we found eight genes (ANKRD13C, ARL5A, ATL3, PAWR, PDCD6IP, SLC16A7, TFAM, UBP1) presenting a significant inverse correlation with miR-181a/b expression also in melanoma A375 sensitive cells." (PMID 33670365, 2021).
multiple sclerosis (1 paper, 2021). A progressive autoimmune disorder affecting the central nervous system resulting in demyelination. "PAWR (pro-apoptotic WT1 regulator) is a pro-apoptotic gene that was among the top differentially expressed genes in peripheral blood mononuclear cells (PBMCs) from multiple sclerosis (MS) patients and might be involved in the regulation of MS." (PMID 34349791, 2021).
schwannoma (1 paper, 2013). A benign, usually encapsulated slow growing tumor composed of Schwann cells. "Therefore, in schwannoma cells, apoptosis mediated by CAV1-AR-PAWR does not seem to occur due to the downregulation of PAWR mRNA in the tumor cells." (PMID 23354516, 2013).
cancer (21 papers, 2013 to 2024). A tumor composed of atypical neoplastic, often pleomorphic cells that invade other tissues. "PAWR, implicated in various cancers, and S100A8, a regulator of inflammatory responses, further expanded the repertoire of potential therapeutic targets." (PMID 38384278, 2024). "PAWR (Pro-Apoptotic WT1 Regulator) encodes a tumor suppressor protein that selectively induces apoptosis in cancer cells." (PMID 38069262, 2023). "The proapoptotic protein PAWR is capable of inducing apoptosis of cancer cells, sensitizing cancer cells to diverse apoptotic stimuli and causing the regression of tumors in animal models." (PMID 34018701, 2021). "Of the top five most variable age components that are found solely in the diabetic cohort, PAWR is a tumor suppressor gene, inducing selective apoptosis of cancer cells, and may thus be related to association of aging with higher cancer rates." (PMID 35255955, 2022). "Prostate apoptosis response-4 (Par-4), encoded by the PAWR gene (also named PRKC apoptosis WT1 regulator), is a therapeutically promising tumor-suppressor protein that can selectively induce apoptosis in cancer cells." (PMID 38886572, 2024). "Our previous study has reported that dsPAWR-435, a small dsRNA targeting PAWR promoter, can up-regulate PAWR gene expression effectively in human cancer cells." (PMID 34220332, 2021). "We previously reported that several small double-stranded RNAs (dsRNAs) targeting the PRKC apoptosis WT1 regulator (PAWR) promoter can up-regulate PAWR gene expression effectively in human cancer cells." (PMID 34220332, 2021). "Our attempts with dsRNAs targeting the PAWR promoter have successfully induced transcriptional activation of the PAWR gene in human cancer cells." (PMID 34220332, 2021). "Consistent with result for some other tissues, PAWR was expressed in the cytoplasm in cells of normal fallopian tubes, while there was both cytoplasmic and nuclear expression of PAWR in cancer samples." (PMID 33317551, 2020). "Par-4 is a pro-apoptotic protein of approximately 38 kDa, encoded by PAWR gene (PKC apoptosis WT1 regulator) and expressed ubiquitously in normal and cancer cells." (PMID 25685660, 2015). "Here, we found that PAWR was expressed ubiquitously in normal and cancer tissues." (PMID 33317551, 2020). "Prostate apoptosis response-4 (Par-4, also known as PAWR) is a ubiquitously expressed tumor suppressor protein that induces apoptosis selectively in cancer cells, while leaving normal cells unaffected." (PMID 39273065, 2024). "All other coding genes LPHN2, EFNA1, ISL1, TRIM29, PAWR, and GOSR2 were differentially up- or downregulated in different cancers." (PMID 36352089, 2022). "Experimental evidence indicates that prostate apoptosis response-4 (Par-4, also known as PAWR) is a key regulator of cancer cell survival and may be a target for cancer-selective targeted therapeutics." (PMID 23760770, 2013).
tumor (16 papers, 2011 to 2025). "This is an intergenic SNP that lies between PAWR and PPP1R12A and it may be in linkage disequilibrium with functional variants in either gene, although PAWR as a tumor suppressor is a more likely candidate." (PMID 21358824, 2011). "Prostate apoptosis response-4 (Par-4, also known as PAWR) is a tumor suppressor that is ubiquitously expressed in various cell types and vertebrate tissues." (PMID 35425699, 2022). "Among the tumor suppressor proteins expressed ubiquitously by normal cells and tissues, Prostate apoptosis response-4 (Par-4, also known as PAWR) exhibited both intracellular and extracellular pro-apoptotic functions." (PMID 28076793, 2017). "The strongest signal was discovered at the SNP rs12827748, located upstream of the PAWR gene, a tumor suppressor, which is amply expressed in the prostate." (PMID 21358824, 2011). "Furthermore, the survival associations for COL1A2, PAWR and MED10 suggest potential tumor-suppressive roles, supporting their roles in tumor progression as they are upregulated in adenocarcinoma samples in our analysis." (PMID 40362431, 2025). "PAWR is also an activator of myosin phosphatase and can dephosphorylate merlin in non-mutated tissues and recover its anti-tumor function." (PMID 23354516, 2013).
adenocarcinoma (1 paper, 2025). A common cancer characterized by the presence of malignant glandular cells. "In adenocarcinoma, COL1A2, CEBPZ, MED10 and PAWR were overexpressed, suggesting their involvement in advanced disease progression." (PMID 40362431, 2025).
PAWR also shares sentences with these, for which no sentence is quoted: Alzheimer disease (2 papers); breast carcinoma (2); colon cancer (2); pancreatic cancer (2); astrocytomas (1); gastric tumor (1); head and neck cancer (1); liposarcoma (1); Myelodysplasia (1); Obesity (1); prostate tumor (1).